TC2N (tandem C2 domains, nuclear)
Diseases named in the same sentence as TC2N in open-access papers (continued):
Sharing a sentence is not in itself a finding about the gene and the disease.
cancer (10 papers, 2012 to 2025). A tumor composed of atypical neoplastic, often pleomorphic cells that invade other tissues. "On the other hand, the protein encoded by TC2N has crucial roles in cellular metabolism, proliferation and cancer." (PMID 36765901, 2023). "Tandem C2 domains nuclear protein (TC2N) is a tandem C2 domain-containing protein that is differentially expressed in several types of cancers and is closely associated with tumorigenesis and tumor progression." (PMID 34925334, 2021). "Some of the tumour types (such as DLBC and PRAD) showed +ve/strong +ve correlation of cancer causing genes with TC2N in almost all the cancer pathways investigated, strongly suggesting a potential role of TC2N in carcinogenesis of those tumours." (PMID 33247676, 2020). "It is therefore highly relevant to investigate TC2N molecular profile and associated circuitry to better understand its role in various cancers." (PMID 33247676, 2020). "In this study, we investigated TC2N mRNA expression, its promoter methylation status, effect of TC2N transcription on patients’ prognosis, correlation between TC2N mRNA expression and other cancer genes, TC2N functional protein partners and somatic mutations in TC2N gene in pan-cancer." (PMID 33247676, 2020). "Our previous study preliminary inquired the anti-cancer role of TC2N in BC, a novel tandem C2 domain-containing protein turned into oncogene in many human cancers." (PMID 38167440, 2024). "Subsequently, the prognostic significance and pivotal role of TC2N in many cancers have been disclosed." (PMID 38167440, 2024). "This article provides an exploration of TC2N as a potential target for the diagnosis and treatment of different types of cancers." (PMID 34925334, 2021). "In this review, we summarize the clinical characteristics of TC2N-positive cancers and potential mechanisms of action of TC2N in the occurrence and development of specific cancers." (PMID 34925334, 2021). "Our findings unravel several un-explored avenues related to the role of TC2N in tumourigenesis of several cancers, suggesting TC2N as an important player and a potential candidate for tumour-therapy." (PMID 33247676, 2020). "Taken together, these data exhibit first ever pan-cancer expression analyses for TC2N expression and therefore delineate possible role of TC2N in these cancers." (PMID 33247676, 2020). "Levels of TC2N promoters were significantly higher in several cancers including the cancers for which we found downregulation of TC2N mRNA levels." (PMID 33247676, 2020). "We further investigated correlation between TC2N mRNA expression and its promoter methylation levels in pan-cancer." (PMID 33247676, 2020). "TC2N transcription was positively correlated with transcription of several other cancer genes including genes from Myc, cell-cycle, Nrf2, Wnt, PI3K, Hippo, Notch, TGFβ and RAS/RTK pathways." (PMID 33247676, 2020). "In order to investigate TC2N mRNA expression patterns, data from TCGA database were analyzed across 33 cancer types compared to matched normal tissues from the TCGA database as well normal controls available at the GTEx database." (PMID 33247676, 2020). "We investigated TC2N expression correlation with other cancer genes in all 33 cancers enlisted in the TCGA database." (PMID 33247676, 2020). "Due to the fact that many genes have a dual role in cancer, we intend to further explore the precise role of TC2N in cancer development and progression." (PMID 31142739, 2019). "Subsequently, we and other researchers both domestically and internationally have gradually revealed the oncogenic roles and mechanisms of TC2N in malignancies such as liver cancer, gastric cancer, and glioma, establishing the significant position of this gene in cancer." (PMID 39849581, 2025). "Tandem C2 domains, nuclear (TC2N) is a C2 domain-containing protein that belongs to the carboxyl-terminal type (C-type) tandem C2 protein family, and acts as an oncogenic driver in several cancers." (PMID 38167440, 2024).
cancer (continued). "In this study, we investigated correlation between TC2N mRNA expression and various cancer genes." (PMID 33247676, 2020). "Moreover, our findings also suggest TC2N interaction with many cancer genes in well-known cancer pathways." (PMID 33247676, 2020). "Taken together, we propose that TC2N may serve as an important player in carcinogenesis, prognosis and therapeutics of several cancers." (PMID 33247676, 2020). "In conclusion, we present novel findings with respect to TC2N molecular circuitry in pan-cancer." (PMID 33247676, 2020). "We identified a range of genetic alterations in the TC2N gene in several cancers." (PMID 33247676, 2020). "In order to investigate potential role of TC2N mRNA levels in tumour prognosis and patient survival, Kaplan-Mayer curves were generated for pan-cancer using tumour data sets from the TCGA database." (PMID 33247676, 2020). "Our analyses highlight potential role of TC2N in carcinogenesis of various cancers." (PMID 33247676, 2020). "For years, the role of TC2N in cancer remains completely unexplored." (PMID 31142739, 2019). "Due to TC2N expression showed differences between each BC molecular subtype, we further evaluated the possible correlation between TC2N and FASN expression in the four cancer subtypes." (PMID 38167440, 2024). "Altogether, we demonstrate a previously unidentified role and mechanism of TC2N in regulation of lipid metabolism and PTEN neddylation, providing a potential therapeutic target for anti-cancer." (PMID 38167440, 2024). "In OB/OW subjects three genes were consistently overexpressed (TC2N, MIRLET7A2 and CLDN10) in the PP adipose tissue of men with cancer (EPCa or OCPCa), compared to BPH." (PMID 23009291, 2012). "However, it is not clear whether TC2N has any role in cancer." (PMID 30254375, 2019).
tumor (8 papers, 2019 to 2025). "In our previous studies, we have identified a C2 domain-containing protein TC2N in lung cancer, and further uncovered its expression, biological function and underlying molecular mechanisms in regulation of tumor growth and metastasis." (PMID 38167440, 2024). "Gene encoding tandem C2 domains nuclear protein (TC2N)—a putative C2 domain-containing protein—has recently been shown to function both as an oncogene and a tumor suppressor gene." (PMID 34925334, 2021). "To gain insight into this issue, we tried to investigate the possible downstream signaling, and found that the different effects on tumor growth of ectopic expression of TC2N are associated with PI3K-AKT signaling." (PMID 31142739, 2019). "This suggests that TC2N expression may be associated with the degree of tumor differentiation." (PMID 39849581, 2025). "To further investigate the relationship between TC2N expression and tumor differentiation in a clinical context, we performed a retrospective analysis on our previous Tissue Microarray (TMA) cohort (Cohort 1) consisting of 272 human lung tumor tissues." (PMID 39849581, 2025). "To evaluate the carcinogenic potential of TC2N, we used urethane, a tumor inducer, and found that TC2N knockout mice were more resistant to urethane-induced lung tumorigenesis compared to TC2N heterozygous and wild-type mice." (PMID 39849581, 2025). "Actually, EGFR, ERK, STAT3, and FAK1 are also dominant players in tumorigenesis, we supported that TC2N upregulated phosphorylation levels of these oncoproteins, which in turn conferred oncogenic signals to promote tumor initiation." (PMID 39849581, 2025). "Considering that we aim to elucidate the role of TC2N in tumor origin and that CSCs are key to tumor occurrence, we explored the relationship between TC2N expression and tumorigenesis in a CSC stemness point of view." (PMID 39849581, 2025). "Consistently, TC2N overexpression impeded tumor growth, accompanying decreased fat content in tumor tissues." (PMID 38167440, 2024). "Our later study found that TC2N has a opposite function in BC, its act as a tumor suppressor by inhibiting tumor growth via PI3K-Akt signaling." (PMID 38167440, 2024). "Despite the emerging roles of TC2N in tumor suppression, only very little is known about its function and underlying mechanism." (PMID 38167440, 2024). "Regarding the mechanism of the tumor-suppressing role of TC2N, we show that TC2N restrains fatty acid synthesis by regulating FASN at protein level." (PMID 38167440, 2024). "Of all the 33 tumour types, 6 tumours exhibited significant role of TC2N mRNA levels in tumour prognosis." (PMID 33247676, 2020). "We also report increased mRNA expression in all stages, nodal metastasis and various histological types for CHOL and STAD suggesting a role of TC2N in the degree of malignancy for these tumours." (PMID 33247676, 2020). "It is therefore highly relevant to investigate TC2N molecular partners/mechanisms on a larger scale including a wider range of tumour types." (PMID 33247676, 2020). "It is therefore possible that TC2N perform similar pro-tumour functions in 5 tumour types identified herein with high TC2N mRNA levels." (PMID 33247676, 2020). "Consistently, upregulation of TC2N dramatically reduced, whereas knockdown of TC2N rescued, the cell proliferation in vitro and tumor growth in vivo." (PMID 31142739, 2019). "The critical role of TC2N in tumor progression motivated us to identify the genes that are regulated by TC2N." (PMID 30254375, 2019). "In summary, we here provide evidence that high expression of TC2N inhibits cell proliferation and tumor growth and correlates with a better prognosis in BC." (PMID 31142739, 2019). "The results revealed that the knockdown of TC2N resulted in an increase in apoptotic cells in tumor tissues." (PMID 30254375, 2019). "Consistently, we also observed that TC2N was highly expressed in tumor tissues compared to peritumoral tissues." (PMID 30254375, 2019).
tumor (continued). "TC2N expression significantly increased with decreasing tumor differentiation." (PMID 39849581, 2025). "Certainly, we cannot exclude the potential role of TC2N in tumor differentiation/dedifferentiation." (PMID 39849581, 2025). "Furthermore, histological results indicated that TC2N expression is low in well-differentiated tumor tissues and high in poorly differentiated tumor tissues, seeming to suggest a potential role for TC2N in regulating cell differentiation." (PMID 39849581, 2025). "Considering the important role of the C2 domain in regulating corresponding protein’s exocytosis function, we regarded TC2N as a secreted protein that could translocate to extracellular microenvironment and affect tumor cell phenotype." (PMID 38167440, 2024). "Prior to this, we first discuss whether the TC2N/FASN axis-mediated tumor progression is BC subtype-dependent?" (PMID 38167440, 2024). "In this study, we have identified TC2N as a tumor metastasis and stemness-related gene in BC." (PMID 38167440, 2024). "Combining that only a part of FASN level was recused after C2B domain deletion, we therefore speculated that cytoplasmic TC2N also exerts a tumor-suppressive function in BC." (PMID 38167440, 2024). "Our findings provide a novel function and mechanism in TC2N-mediated tumor progression." (PMID 38167440, 2024). "Importantly, we here report TC2N to be a tumor suppressor that blocks fatty acid synthesis through preventing neddylated PTEN-mediated FASN stabilization." (PMID 38167440, 2024). "Through further statistical analyzing the association of TC2N protein expression with clinicopathological characteristic, we found TC2N expression is related to clinical stage, differentiating degree, tumor invasion depth, molecular subtype, especially lymph node metastasis and distant metastasis." (PMID 38167440, 2024). "TC2N mRNA expression was differentially regulated in 9/33 TCGA tumour types." (PMID 33247676, 2020). "TC2N expression was inversely correlated with tumor size, which suggested that TC2N may be involved in the regulation of tumor growth." (PMID 31142739, 2019). "Oppositely, high TC2N expression predicts favorable prognosis in BC, suggesting that TC2N may be a tumor suppressor in BC." (PMID 31142739, 2019). "Accordingly, we suspect that TC2N may be a potential tumor suppressor gene in BC." (PMID 31142739, 2019). "Patients with lower TC2N expression showed a shorter overall survival (and thus poor prognosis) in KIRC, MESO, SARC and SKCM tumour types." (PMID 33247676, 2020). "Patients with higher TC2N mRNA levels showed a shorter overall survival (and thus poor prognosis) in LGG and PAAD tumour types." (PMID 33247676, 2020). "To investigate the relationship between TC2N and BC, we first assessed the expression of TC2N between tumor and non-tumor tissues by analyzing the published datasets, Oncomine." (PMID 31142739, 2019). "Based on IHC results, the protein expression of TC2N was markedly upregulated in tumor tissues compared to adjacent normal tissues non-tumor tissues." (PMID 31142739, 2019). "Based on the extremely low expression of TC2N in normal lung tissue and adjacent non-cancerous tissue, we speculate that a sufficient level of TC2N expression or carcinogenic stimuli may be required to drive tumor initiation." (PMID 39849581, 2025).
TC2N also shares sentences with these, for which no sentence is quoted: colon cancer (1 paper); lymph node metastasis (1); mesothelioma (1); metastatic tumors (1); ovarian serous cystadenocarcinoma (1); pancreatic adenocarcinoma (1); pheochromocytoma (1); rectal adenocarcinoma (1); sarcoma (1); skin-cutaneous-melanoma (1); stomach-adenocarcinoma (1); thymoma (1); thyroid carcinoma (1); uterine carcinosarcoma (1).